CRP (C-reactive protein)
Diseases named in the same sentence as CRP in open-access papers (continued):
Sharing a sentence is not in itself a finding about the gene and the disease.
ulcer (continued). "Colonoscopies were performed in 8 of 13 patients in remission, revealing a totally healthy mucosa in 4, mild ulcers in 3, and active ulcers in 1 patient with high levels of CRP." (PMID 37513532, 2023). "Predictors of a more aggressive disease course are young age at diagnosis, extensive disease, extra-intestinal manifestations, presence of endoscopic signs of disease activity (e.g., ulcers), and elevated inflammatory biomarkers (FC and C-reactive protein)." (PMID 32911840, 2020). "We found higher CRP levels of borderline statistical significance in the ulcer group, while fibrinogen concentrations were similar." (PMID 31432450, 2019). "The levels of PCT, ESR and CRP were significantly higher in patients with class IV foot ulcer compared to those with class III ulcers (p<0.001)." (PMID 31555767, 2019). "In diabetic foot ulcers, a CRP concentration threshold of 17 mg/L can be used to distinguish between grade 1 (uninfected) and grade 2 (mild severity infection) ulcers, while in venous ulcers the infection threshold was set to 20 mg/L." (PMID 29257113, 2017). "Our findings suggest that a combination of MMP-9, CRP, VEGF, and ICAM-1 may serve as an effective biomarker panel for early risk assessment and ulcer progression monitoring." (PMID 40364880, 2025). "In addition to ulcer severity and infection, we examined the correlation between fibrinogen and clinical parameters, uncovering significant relationships with CRP, fasting blood glucose, and serum albumin." (PMID 40151482, 2025). "However, animals pretreated with CRP exhibited markedly higher SOD activity compared to the ulcer control group." (PMID 40647169, 2025). "Among the biomarkers assessed, MMP-9 and CRP demonstrated the highest diagnostic accuracy for DFU detection, while VEGF and ICAM-1 showed promise as early indicators of vascular impairment in pre-ulcer patients." (PMID 40364880, 2025). "However, the administration with SeNPs during seven consecutive days significantly (p < 0.01) improved plasma CRP levels in ulcer-group." (PMID 41357879, 2025). "Those with lower GNRI values had higher CRP levels [11.3 (2.9–44.5) mg/L, 4.0 (1.0–14.0) mg/L, and 3.0 (1.0–12.0) mg/L in T1, T2, and T3, respectively; p < 0.0001] and a higher prevalence of ulcer/gangrene (49.6%, 44.6%, and 27.7% in T1, T2, and T3, respectively; p < 0.0001)." (PMID 38202133, 2023). "Nonetheless, increased CRP levels in patients with ulcers might indicate the presence of infection in affected tissues." (PMID 31432450, 2019). "Patients who healed their ulcers also had lower serum CRP at visit 1 (p<0.05), lower interleukin-1 alpha (IL-1α) at visit 1 (p<0.05) and visit 4 (p<0.05), lower Granulocyte-Macrophage Colony-Stimulating Factor (GM-CSF) at visit 1 (p<0.05) and marginally lower GM-CSF at visit 4 (p=0.072)." (PMID 24358275, 2013). "Importantly, we have shown that SeNPs pretreatment reduces CRP thereby promoting ulcer healing." (PMID 41357879, 2025). "Age at diagnosis, ulcer recurrence, atopic dermatitis history, white blood cell count, blood eosinophil count, platelet count, serum albumin level, iron level, erythrocyte sedimentation rate, and C-reactive protein level differed significantly among the 5 groups (all p < 0.05)." (PMID 32819298, 2020). "C-reactive protein (CRP), WBC, neutrophils, ulcer length and width, and surface area were also reduced in the vildagliptin group compared to placebo (p < 0.05)." (PMID 36456992, 2022). "In addition, fasting plasma glucose and HbA1c levels were significantly higher in pre-ulcer and ulcer groups compared to controls (p < 0.001), with HbA1c showing strong positive correlations with MMP-9, CRP, and other biomarkers." (PMID 40364880, 2025). "Similarly, those with higher CRP also had lower GNRI values (94.3 ± 9.4, 93.1 ± 9.7, and 89.1 ± 10.1 in T1, T2, and T3, respectively; p < 0.0001) and higher prevalence of ulcer/gangrene (23.5%, 34.5%, and 63.9% in T1, T2, and T3, respectively; p < 0.0001)." (PMID 38202133, 2023).
ulcer (continued). "The size of intestinal ulcers (> 1 cm), Hb < 123 g/L, and elevated inflammatory biomarker levels (CRP > 44 mg/L) were correlated with non-healing ulcers in univariate analysis but not in multivariate analysis." (PMID 31779646, 2019). "Nonetheless, when corrected for age, there was a significant increase in CRP in patients with lower leg ulcers compared to those without ulcers, suggesting increased inflammation, which is a feature of diabetic skin ulceration." (PMID 23484147, 2013). "Finally, the lack of data on potential interactions between CRP and conventional ulcer medications (e.g., proton pump inhibitors) hinders clinical translation, necessitating future drug combination studies." (PMID 40647169, 2025). "There were significant differences in CRP (P = 0.01), erythrocyte sedimentation rate (P = 0.008), fecal calprotectin (P = 0.01), and albumin (P = 0.02) between patients without and with radiologic ulcers." (PMID 39292244, 2024). "There were significant differences in C-reactive protein, erythrocyte sedimentation rate, fecal calprotectin, albumin, maximum bowel wall thickness, and length of disease between patients without and with radiologic ulcers (P < 0.05)." (PMID 39292244, 2024). "The proportions of patients with previous intestinal resection, perianal involvement, and CRP > 4 mg/L were significantly higher in the ulcer group than in the non-ulcer group (47.6% vs. 20.0% (p = 0.009), 42.9% vs. 20.0% (p = 0.027), 28.6% vs. 8.6% (p = 0.022), respectively)." (PMID 35508963, 2022). "The study conclusively identified several key predictors for major LEA in patients with DFUs, notably advanced ulcer severity (Wagner's grade ≥ 5), absent peripheral pulsation, clinical evidence of infection, and elevated inflammatory markers (ESR and CRP)." (PMID 39935923, 2025). "However, according to the regression analysis performed, insulin levels are important variables for the ulcer size in the RSV group, whereas CRP values are not relevant to study outcome." (PMID 24701359, 2014).
anxiety disorder (47 papers, 2014 to 2026). A category of psychiatric disorders which are characterized by anxious feelings or fear often accompanied by physical symptoms associated with anxiety. "Our results of an association between CRP and anxiety disorder aligns with a relatively large body of literature connecting systemic inflammation to psychiatric disorders." (PMID 40485662, 2025). "Previous studies have documented associations between inflammation and psychiatric symptoms, and elevated levels of IL-6 and CRP have been linked to greater symptom severity in various anxiety disorders." (PMID 39063640, 2024). "The Lifelines study with 54,326 participants has demonstrated that anxiety disorders were associated with higher serum C-reactive protein (CRP) levels after adjusting for all covariates." (PMID 35463036, 2022). "An association was observed between other anxiety disorders (including panic and generalised anxiety disorders) and CRP (OR: 1.164 [95% CI: 1.096–1.236])." (PMID 35028602, 2022). "As reported in previous study, elevated levels of pro-inflammatory cytokine C-reactive protein (CRP) was associated with anxiety disorders." (PMID 33329133, 2020). "Specifically, anxiety disorders are associated with elevated levels of the pro-inflammatory cytokine C-reactive protein (CRP), which can cause chronic inflammation and contribute towards the disorder development ⁠." (PMID 30043270, 2018). "Afterbasic adjustment, higher basal levels of CRP and IL-6 were associated with thepresence of current depressive/anxiety disorder." (PMID 27244234, 2016). "Individual level MR was numerically associated with a causal effect of CRP on any anxiety disorder." (PMID 40348744, 2025). "Additionally, physical activity reduces systemic inflammation by lowering pro-inflammatory cytokines (IL-6, TNF-α, CRP), which are linked to the onset and progression of anxiety disorders." (PMID 41246056, 2025). "Genetic analyses suggest that IL-6 signaling could be relevant for memory, and that the association between CRP and anxiety disorders could be potentially causal." (PMID 38699368, 2024). "Genetic analyses suggest that IL-6 signaling could be relevant for memory, and that the association between CRP and anxiety disorders could be causal." (PMID 38699368, 2024). "Individual level MR provided weak evidence for a causal effect of CRP on any anxiety disorder." (PMID 38699368, 2024). "Furthermore, a large cohort study looking at the association between anxiety disorders and inflammation identified an elevated level of CRP in male patients with anxiety disorders." (PMID 29181395, 2017). "As we have identified elevated CRP and GlycA to be predictive of future anxiety disorder diagnosis, further research is warranted to assess whether the prophylactic use of anti-inflammatory drugs is associated with a reduced risk of anxiety disorder onset." (PMID 40485662, 2025). "Within AUD, greater MD severity was associated with higher GGT, ALT, CRP, NFS and any DSM anxiety disorders (p < 0.05)." (PMID 41780539, 2026). "Whilst there is research identifying a link between anxiety disorder and elevated inflammation, this study is one of the first to demonstrate the potential of CRP and GlycA as predictive biomarkers." (PMID 40485662, 2025). "In the context of anxiety disorders, a meta-analysis demonstrated that CRP concentrations were significantly higher in individuals with generalized anxiety disorder compared to controls." (PMID 39452916, 2024). "Studies have found that patients with anxiety disorders tend to have elevated levels of CRP, lymphocyte count, and T cell count." (PMID 39902242, 2024). "The “other anxiety disorders” group were 1.164 times more likely to have a CRP above 3 ​mg/L in model 1 with a p value ​< ​0.001." (PMID 35028602, 2022).
anxiety disorder (continued). "In a previous study, the prevalence rates for low-grade systematic inflammation, which was defined by serum CRP > 3mg/L, in unipolar mood disorder and in neurotic disorders, including anxiety disorders, were 16% and 22%, respectively." (PMID 32260096, 2020). "Although we were only able to meta-analyse CRP, meta-analyses of different cytokines in other anxiety disorders have been conducted with larger effect sizes." (PMID 31326932, 2019). "Meta-analyses suggest that the prospective risk of incident coronary heart disease (CHD) is increased in individuals with an anxiety disorder, including phobic anxiety, as well as in those with elevated levels of inflammatory measures, including CRP and TNF-α." (PMID 25875094, 2015). "The level of inflammatory biomarkers, tumor necrosis factor (TNF)-α, interleukin (IL)-6 and C-reactive protein (CRP) among people with anxiety disorders have been studied by observing how they interact with neurotransmitter systems, especially serotonin and dopamine, it influences mood and behavior." (PMID 40421256, 2025). "Genetically-proxied CRP (cis) was non-significantly associated with a causally increased risk of any anxiety disorders (beta: 0.12, p = 0.054, N = 22,154) and negative affect (beta: 0.27, p = 0.16; N = 23,268)." (PMID 40348744, 2025). "In individuals with current depressive or anxiety disorders compared to healthy controls, elevated levels were observed in CRP, IL-6, IL-8, IL-18, MCP-1, MIP-1α, MIP-1β, MMP2, and TNF-β, while TNF-α, IL-10, IFN-γ, IL-2, and IL-4 levels either showed no significant elevation or were lower." (PMID 39273641, 2024). "In the non-genetic analyses, circulating CRP levels was associated with a modestly increased likelihood of meeting criteria for anxiety disorders, although this association was substantially attenuated following adjustments for covariates." (PMID 38699368, 2024). "There was weak evidence that genetically-proxied CRP (cis) causally increased the risk of any anxiety disorders (beta: 0.12, p=0.054, N=22,154), and little evidence on negative affect (beta: 0.27, p=0.16; N=23,268)." (PMID 38699368, 2024). "Similarly, CBT has been associated with reductions in inflammation, as indicated by lower concentrations of CRP and other peripheral inflammatory markers in mood and anxiety disorders." (PMID 39063640, 2024). "We found associations between stress/adjustment disorders (F43) and “other anxiety disorders” (F41) (e.g. generalised anxiety disorder, panic disorders) and CRP after accounting for the following potential confounders: age, sex, ethnicity, deprivation and education level." (PMID 35028602, 2022). "The first model included the six clinical and immune variables significantly different between the study groups: state anxiety, trait anxiety, total score CTQ, CRP, total white cells and neutrophils numbers." (PMID 32699209, 2020). "As for PSAC-induced anxiety, it has been linked with elevated pro-inflammatory markers, such as in a cohort study showing that elevated CRP was observed in male patients with anxiety disorders; another study found increased TNF-α in patients with anxiety disorders." (PMID 39802655, 2025). "Higher levels of pro-inflammatory peripheral cytokines have been identified both in models of anxiety disorders (tumor necrosis factor-α [TNF-α] and interleukin [IL]-1 β, IL-6), as well as mood and anxiety disorders patients (c-reactive protein [CRP], TNF-alpha, IL-1, IL-6,)." (PMID 34680430, 2021). "Another inflammatory marker, C-reactive protein, has been shown to be significantly higher in men with anxiety disorders than in men without, even taking into account other disease factors and lifestyle." (PMID 33920547, 2021).
anxiety disorder (continued). "We tested in ≈ 55,098 (59% female) individuals from the Dutch Lifelines cohort the concurrent/prospective associations of C-reactive protein (CRP) with: depressive and anxiety disorders; positive/negative affect; and attention, psychomotor speed, episodic memory, and executive functioning." (PMID 39149475, 2024). "The GWAS summary data on MDD, anxiety disorder, PTSD, AN, histamine, and CRP were not available in our included studies, however, low bias and Type 1 error rates were found." (PMID 38352653, 2024). "Subjects with atypical MDD exhibited higher CRP levels than those subjects without MDD (mean difference = 1.56 mg/L) or nonatypical MDD (mean difference = 1.40 mg/L) control, even after adjusting for confounders, anxiety disorders, BMI, and smoking." (PMID 35163538, 2022).
Ascites (47 papers, 2016 to 2026). Accumulation of fluid in the peritoneal cavity (between the layers of the peritoneum that lines the abdomen). "Elevated CRP/albumin ratio was also associated with complications like multi-organ failure OR: 2.31 [1.3–4.2], duodenal thickening OR: 2.25 [1.2–4.2], and ascites OR: 2.90 [1.5–5.6]." (PMID 36268355, 2022). "In the R-SILC + 1 group, one child exhibited peritoneal effusion, showing hyperpyreia and increased CRP levels on the 1st day after surgery, which recovered after one week of anti-infection treatment with cefoperazone." (PMID 39363967, 2024). "In the study group, the clinical variables best able to predict death were MELD, ascites, creatinine, age, and CRP." (PMID 37973887, 2023). "All blood cell ratios were significantly associated with ascites development within univariate analysis (NLR, LLR, MLR, PLR) as well as an elevated CRP (HR 10.9, CI 4.33-27.4, P < 0.001)." (PMID 36989885, 2023). "In the univariate analysis of variables for the OS for all cases, ECOG-PS 0 (P = 0.0059), presence of ascites (P = 0.0106), C reactive protein (CRP) ≥0.5 mg/dl (P = 0.0121), PMI-high (P < 0.0001), and FRPM-high (P = 0.0341) were significant factors." (PMID 36313034, 2022). "F(stage IV) = 25.678 ∗ ascites − 0.001 ∗ CA724 + 0.002 ∗ CA242 + 9.091 ∗ TT + 0.048 ∗ PLT + 0.33 ∗ CRP + 0.002 ∗ AST − 108.563." (PMID 29967637, 2018). "The NAR ≥ 1.40 group had a significantly higher proportion of male, a higher incidence of infection, ascites, jaundice, and higher CRP, ALT, AST, TB, INR, WBC, Neutrophil, NAR, Cr, PLT, and MELD scores, but lower serum sodium and albumin than the NAR < 1.40 group." (PMID 38007536, 2023). "It is worth mentioning that in this study, we found that the high NAR group had significantly higher proportion of male, a higher incidence of infection, ascites, jaundice, and higher CRP, ALT, AST, TB, INR, WBC, Neutrophil, Cr, PLT, and MELD scores, but lower serum sodium than the low NAR group." (PMID 38007536, 2023). "Accordingly, it may explain why the significant lower AUCs for CRP (0.645–0.676) in the current study for diagnosis of ascitic fluid infection." (PMID 30097024, 2018). "Again, those prescribed antibiotics had higher prevalence of ascites and HE and higher creatinine, WCC, and CRP." (PMID 35970815, 2023). "In the present study, we screened 7 indexes (CA724, CA242, TT, PLT, CRP, AST, and ascites) and got a discriminant for predicting stage." (PMID 29967637, 2018). "CRP, LDH, Ca2+, and peritoneal effusion are independent predictors of HTG-SAP." (PMID 38066493, 2023). "The univariate analysis revealed that nine variables including the baseline serum PLT level, the baseline CRP level, the baseline AFP level, the tumor size, the tumor number, the 8-and-14 grade, ascites, the ALBI grade, and the ALBI-AS grades were evaluated to be associated with overall survival." (PMID 35845571, 2022). "When only patients with SIRS were analyzed, univariate Cox regression showed that survival was related to the presence of ascites, HE, bacterial infection, sodium, albumin, INR, total bilirubin, creatinine, leukocyte count, CRP, MELD score, ACLF, and Child-Pugh C." (PMID 33987144, 2021). "Differences in the age, sex, etiology, ALT, BUN, Cr, NH3, Plt, WBC, CRP, P3P, and M2BpGi in patients with high versus low EA were not significant, but ascites was present in more patients with high EA than in those with low EA (p < 0.05)." (PMID 32422875, 2020). "Patients prescribed antibiotics without infection had similar age, gender, presence of ascites, and serum albumin to those not, but had significantly increased variceal bleeds, HE, creatinine, WCC, and CRP." (PMID 35970815, 2023). "It comprised a total of six indicators, namely, CRP, LDH, Ca2+, PCT, the presence or absence of peritoneal effusion, and the Balthazar grading." (PMID 38066493, 2023).
Ascites (continued). "Patients prescribed NSBBs at baseline had similar age, gender, presence of ascites, MELD score serum albumin and CRP to those not, but significantly increased incidence of suspected variceal bleeds and serum creatinine and significantly reduced WCC." (PMID 36407574, 2023). "Finally, four independent predictors of HTG-SAP, including CRP, LDH, Ca2+, and the presence or absence of ascites, were obtained." (PMID 38066493, 2023).